NPY (neuropeptide Y)
Diseases named in the same sentence as NPY in open-access papers (continued):
Sharing a sentence is not in itself a finding about the gene and the disease.
tumor (102 papers, 2000 to 2026). "NPY is strongly linked to cancer progression, influencing tumor cell growth, invasion, migration, and angiogenesis through interactions with its receptors." (PMID 41154659, 2025). "Along with other hormone peptide receptors overexpressed in human cancer, NPY favors in vivo tumor labeling for diagnostic and therapeutic purposes." (PMID 39458969, 2024). "Analysis of the NPY system associations with ERG expression revealed higher Y5R EI in ERG-positive PCa than in ERG-negative tumours (p = 0.024)." (PMID 36583743, 2023). "Several studies suggest that the NPY axis is involved in PCa biology, revealing different associations with genetic alterations, histology, tumour biochemical recurrence and patients’ outcome." (PMID 36583743, 2023). "It has been confirmed that NPY has multiple effects related to cancer biology, such as stimulating tumor-associated angiogenesis, cell proliferation, migration and chemoresistance, as well as regulating the differentiation of stem cells." (PMID 36010960, 2022). "Based on the high degree of presentation across the NPY protein across 68/84 HLA alleles, its high level of differential expression, and its role in promoting tumor growth, we prostulate that NPY is a promising candidate for vaccination strategies." (PMID 32256484, 2020). "The upregulation of VEGF and down regulation of NPY can serve as potential prognostic and diagnostic markers for the well differentiated tumor type of young and old men." (PMID 33575208, 2020). "Cell-free circulating tumor (ct) DNA was measured as either the fraction with Neuropeptide Y (NPY) methylated DNA or KRAS/NRAS/BRAF mutated ctDNA." (PMID 31731482, 2019). "Normally, a lower plasma concentration of leptin is associated with higher NPY secretion; however, NPY pathways have been reported to be dysfunctional in anorectic tumour-bearing rats." (PMID 26508820, 2015). "Neuropeptide Y (NPY) is found at high concentrations in neural crest-derived tumours and has been implicated as a regulatory peptide in tumour growth and differentiation." (PMID 10901366, 2000). "Moreover, depression promotes tumor-associated macrophage infiltration through neuropeptide Y signaling and accelerates tumor progression via activation of the IL-6/STAT3 pathway." (PMID 41409248, 2025). "However, it should be stated that NPY gene activity has been found to be associated with the reduced invasiveness potential of tumor cells in a concentration-dependent manner." (PMID 39599612, 2024). "The dysregulation of the NPY system is associated with various diseases, including diabetes, obesity, retinopathy, inflammatory conditions, neurodegenerative and neuroimmune disorders, and tumours." (PMID 36583743, 2023). "In this study, NPY immunoreactivity loss was progressively higher with advanced tumor stages." (PMID 37373115, 2023). "Hence, the NPY/Y5R axis contributes to the migratory phenotype in a variety of malignancies, implicating its activity as a pan-cancer mechanism underlying tumor cell dissemination." (PMID 33681186, 2020). "In a prospective study, a combined detection of NPY methylation along with tumor‐specific mutations in ctDNA could give similar results to radiographic evaluation, showing that this combined liquid biopsy approach can be used for the follow‐up of mCRC patients during treatment." (PMID 33942482, 2021). "Therefore, MetctDNA could be a promising surrogate marker for tumor follow-up in patients with CRC, which means that WIF1 and NPY could instead be tumor-specific mutations." (PMID 28903450, 2017). "Studies have shown that DOX-P18, an NPY analog delivered via nanocarriers, achieves precise tumor targeting and shows potential in inhibiting growth and metastasis in triple-negative breast cancer (TNBC)." (PMID 41154659, 2025). "Collectively, our results suggest that the energy derived from FAO contributes to supporting tumor growth during brain colonization under a low-BMI condition through the NPY/Y5R signaling axis." (PMID 40595538, 2025).
tumor (continued). "For example, in NB, NPY increases tumor growth in mice xenografts, and high serum NPY correlates with decreased survival, increased metastasis, and disease recurrence in human patients with NB." (PMID 40073121, 2025). "Mechanistically, low BMI activates ghrelin-GHSR signaling, increasing neuronal neuropeptide Y (NPY) secretion, which promotes tumor metabolic reprogramming via NPY-Y5R, facilitating brain colonization." (PMID 40595538, 2025). "For NPY in PCa cells, the number of NPY+ nerves increased and the growth of NPY‐specific neurites increased, which was related to the aggressive behavior of the tumor." (PMID 41415714, 2025). "Our study unveiled a significant increase in neuronal NPY expression and secretion in the brains of low BMI cancer-free subjects and tumor-free mice, as well as in ghrelin-pretreated primary neurons." (PMID 40595538, 2025). "In hepatocellular carcinoma, dipeptidyl peptidase 4-mediated cleavage of NPY amplifies Y5 receptor signaling, contributing to tumor progression." (PMID 41154659, 2025). "COL3A1 contributes to tumor infiltration and poor prognosis, whereas NPY plays a key role in tumor growth and progression." (PMID 39473365, 2025). "In prostate cancer, NPY inhibits the apoptosis of tumor cells through NF-κB, mediating the chemotherapy resistance of the tumor." (PMID 41154659, 2025). "NPY released by cancer cells can act on receptors expressed on immune cells, alter tumor‐related angiogenesis and inflammation, and promote cell growth." (PMID 41415714, 2025). "Recent studies implicate neural-derived factors, such as neuropeptide Y (NPY), in facilitating tumor survival in such stressful microenvironments." (PMID 41163091, 2025). "NPY secreted by the nerves can be also expressed by tumor cells in relation to their molecular characteristics and even the topography of the infiltration." (PMID 39457647, 2024). "Conclusions: [99mTc]HYNIC-cRGDfk-NPY demonstrated rapid blood clearance, renal excretion, and in vivo tumor uptake, highlighting its potential as a tumor imaging agent." (PMID 39458969, 2024). "It has also been shown that tumor hypoxia can upregulate the expression of Y2R and Y5R in Ewing sarcoma and endothelial cells, which sensitizes them to the proliferative effects of NPY." (PMID 38375479, 2024). "The higher in vivo tumor uptake of [99mTc]-HYNIC-cRDGfk-NPY resulted in higher overall tumor-to-muscle ratios, approximately 5.65 ± 0.94 and 7.78 ± 3.20, for MCF-7 and MDA-MB231, respectively, which should translate into images with higher contrast." (PMID 39458969, 2024). "Neuropeptide Y (NPY) is secreted by tumor cells and exerts its effects through various receptors, particularly the Y2 receptor (Y2R)." (PMID 38375479, 2024). "For instance, detailed NPY expression analyses in some types of neoplasia showed increased expression in PNI areas and invasion fronts of prostate and pancreatic cancer." (PMID 39457647, 2024). "Contrary to these observations, NPY gene expression has been found to be higher in tumor tissue, independently of the tumor stage, compared to normal tissue." (PMID 39599612, 2024). "This suggests NPY’s involvement in perineural trafficking and shows topographically dependent phenotypic features of heterogenous tumor masses." (PMID 39457647, 2024). "Serum NPY concentration has been found to be lower in CRC patients, and a decrease in this serum concentration has been associated with tumor size (>5 cm) and body weight loss (>3 kg)." (PMID 39599612, 2024). "Neuropeptide Y is secreted from tumor cells and acts through the Y2 receptor (Y2R) to mediate proliferation and angiogenesis during cancer development." (PMID 39346791, 2024). "A high Y1R density was also observed in the intratumoral blood vessels, and nerve fibers containing NPY were placed close to these vessels and tumor cells." (PMID 37373115, 2023).
tumor (continued). "The cross-talk between cancer progression and the release of peptides belonging to the NPY peptide family from nerve fibers must be fully understood since these peptides regulate tumor development." (PMID 37373115, 2023). "Significant findings have been reported: tumor cells favored the increase in NPY-positive nerve fibers, and the inhibition of NPY promoted the scalation of apoptosis in cancer cells, changes in energetic metabolic pathways, and decreased cell motility." (PMID 37373115, 2023). "Recently it has been shown that in HCC, NPY is secreted by peritumoural hepatocytes and cross talks with overexpressed Y5R in tumour cells." (PMID 36583743, 2023). "NPY expression in transcriptomic analysis has also been shown to be higher in localized tumours, as compared to metastatic PCa." (PMID 36583743, 2023). "NPY, released from tumor cells, controlled the activation of the ERK/MAPK pathway in the latter cells." (PMID 37373115, 2023). "Y2R antagonists blocked HT29 tumor growth and NPY-induced angiogenesis on colonic endothelial cells expressing Y2R." (PMID 37373115, 2023). "In vivo nano-scale bubbles-NPY with doxorubicin and under ultrasound irradiation increased survival time and tumor suppression; minimal damages were observed in the vital mouse organs." (PMID 37373115, 2023). "In perineural areas of cancer infiltration, NPY EI was higher than in other tumour areas (p < 0.0001)." (PMID 36583743, 2023). "We postulate that the NPY system expression differs between benign prostate and cancer tissue and relates to some pathoclinical tumour characteristics." (PMID 36583743, 2023). "Some authors described that ERG-positive PCa cases have higher NPY expression than ERG-negative tumours." (PMID 36583743, 2023). "Most studies regarding the involvement of the NPY peptide family in tumor development have focused on NPY, whereas only incomplete or scarce data are currently available about the involvement of PYY/PP in many cancer types." (PMID 37373115, 2023). "Low NPY gene expression was associated with adverse genomic features and high-risk PCa according to D′Amico's definition, which is composed of PSA, tumour grade and stage status." (PMID 36583743, 2023). "The multifaceted role of the NPY system in tumours and its differential function are driven by the variability in the receptor signalling pathways and peptide expression." (PMID 36583743, 2023). "It has been found that the exposure of tumor cells to NE elicits the secretion of neuropeptide Y (NPY), which in turn facilitates the recruitment of macrophages and subsequent release of interleukin 6 (IL6)." (PMID 38089966, 2023). "The expression of NPY exhibited gradient intensification in the direction of the invasive tumour front, particularly towards EPE and PNI." (PMID 36583743, 2023). "Recent studies revealed an important role of such neuronal NPY, which regulates the tumoural metabolism, apoptosis, motility and therapy resistance via activation of the Y1R." (PMID 36583743, 2023). "Secretion of NPY from PCa cells is activated by noradrenaline which activates β2 adrenergic receptors and drives tumour progression." (PMID 36583743, 2023). "High miR-204 sEVs treatment or tumour-bearing mice indeed reduced mRNA abundance of agouti-related neuropeptide (Agrp) and neuropeptide Y (Npy) in hypothalamic, respectively, thus regulating energy balance and neuroendocrine function." (PMID 37620316, 2023). "NPY levels have been suggested as tumor biomarkers and prognostic factors; however, this must be studied more and confirmed in several tumors." (PMID 37373115, 2023). "Our previous study indicates a tendency towards lower PGP 9.5+ nerve density in the peripheral area of PCa in tumours with a high NPY expression." (PMID 36583743, 2023). "Herein, a transformable prodrug (DOX‐P18) based on neuropeptide Y analogue with tumor microenvironment responsiveness is developed for TNBC treatment." (PMID 37147783, 2023).
tumor (continued). "Neuropeptide Y, which has high endogenous synthesis and release in EWS, was found to be highly associated with tumor biology as a sympathetic neurotransmitter with pleiotropic actions." (PMID 35719404, 2022). "Here, the authors show that neuropeptide Y/Y5 receptor pathway is activated in the hypoxic tumour microenvironment, which results in cytokinesis defects and chromosomal instability, leading to bone invasion." (PMID 35484119, 2022). "We have shown that tumor hypoxia stimulates the NPY/Y5R axis, which leads to RhoA over-activation, cytokinesis defects and polyploidy." (PMID 35484119, 2022). "The aim of the present study was to investigate hypermethylated neuropeptide Y circulating tumor DNA (meth-NPY) as an early biomarker for treatment effect and monitoring in 70 mCRC patients receiving first-line treatment in the FOLFOXIRI-Toco trial." (PMID 36139621, 2022). "The expression of NPY is upregulated in some cancers and supports tumor progression by the activation of various signaling pathways." (PMID 34277455, 2021). "Neuropeptide Y released by tumor cells interacts with receptors on endothelial cells or immune cells, modulating tumor-related angiogenesis and local inflammatory responses." (PMID 34395421, 2021). "In vitro autoradiography with Y1R-positive MCF-7 tumor tissue slices indicated a high specific binding of the 18F-labeled glycopeptide, when binding was reduced by 95% ([Pra4,F7,P34]NPY) and by 86% (BIBP3226, Y1R antagonist) in competitive binding studies." (PMID 34832957, 2021). "Our study revealed NPY expression in the prostate, PCa, and the neural components of the tumor microenvironment: nerves and autonomic ganglia, similarly to previous research." (PMID 34277455, 2021). "Some studies have shown that high expression of NPY can affect the cell cycle and promote tumor invasion and metastasis, also in LUAD." (PMID 34635074, 2021). "Proneuropeptide Y (Pro-NPY, C-terminal of NPY) expression, alone or in combination with the ERG status of the tumor, was associated with an increased risk of PCa specific mortality." (PMID 34948404, 2021). "In vitro, NPY appears to promote tumorigenesis, probably in a neoneurogenesis context in which tumor cells exploit neurotransmitters to generate a pro-tumor environment." (PMID 34627187, 2021). "Here, we have demonstrated for the first time that NPY, both tumor-derived and exogenous, stimulates NB cell migration." (PMID 33681186, 2020). "Administration of NPY decreased tumor volume in Mz-ChA-1 xenograft mice, indicating promising anti-cancer effects against CCA, although current studies are limited and further experimental evidence is required." (PMID 32069926, 2020). "As a sympathetic neurotransmitter highly relevant to tumor biology, neuropeptide Y (NPY) is released from activated peripheral sympathetic neurons under chronic stress or hypoxia." (PMID 32174791, 2020). "Despite the overall low NPY immunoreactivity in the tumor mass, the peptide expression was elevated in tumor cells adjacent to bone invasion areas and directly invading the bone." (PMID 25714031, 2015). "A similar gradient of NPY expression was also observed in SK-ES1 and SK-ES1/NPY shRNA primary tumors, suggesting that bone-derived factors can change the biology of tumor cells." (PMID 25714031, 2015). "We provide direct evidence for the role of NPY in tumor-induced bone degradation and an insight into its potential involvement in ES dissemination." (PMID 25714031, 2015). "The effect of NPY via Y receptors can vary from tumor growth promotion to tumor growth inhibition and induction of apoptosis." (PMID 26153206, 2015). "Strikingly, the mitogenic and pro-migratory effects of NPY are limited to a population of ALDHhigh ES tumor initiating cells, which correlates with increased motility in this cell fraction isolated from SK-ES1-M cells in the current study." (PMID 25714031, 2015).
tumor (continued). "Our previous studies revealed pleiotropic and opposing actions of NPY in ES ranging from Y1R/Y5R-mediated tumor cell death to Y2R/Y5R-mediated angiogenesis and ES cancer stem cell proliferation and migration." (PMID 25714031, 2015). "SK-ES1-M cells also had increased NPY mRNA levels and upon re-introduction to the animals exhibited a significant increase in tumor growth rate as compared to the original SK-ES1 cell line." (PMID 25714031, 2015). "We have shown that hypoxic conditions activate Y2R/Y5R-mediated actions of NPY, which stimulate tumor vascularization and promote ES cell proliferation and migration, the processes known to facilitate tumor dissemination." (PMID 25714031, 2015). "Our findings highlight the importance of assessing NPY functions in tissue environment, uncover its novel role in cancer stem cells and reveal mechanisms governing a hypoxia-induced increase in tumor malignancy." (PMID 24318733, 2013). "Altogether, our results revealed the dynamic nature of NPY actions in ES and critical role of the tumor microenvironment in their regulation." (PMID 24318733, 2013). "Our observations in vitro suggested that the angiogenic activity of NPY in ES is induced in tumor microenvironment by hypoxia." (PMID 24318733, 2013). "In summary, we have shown for the first time fundamental changes that can occur in the NPY/DPPIV system within the tumor microenvironment and their functional consequences." (PMID 24318733, 2013). "Paradoxically, our data indicate that in ES, the EWS-FLI1-driven Y1R/Y5R/NPY autocrine loop stimulates tumor cell death." (PMID 24318733, 2013). "In analogy to somatostatin receptor targeting of tumors, it has been proposed to use NPY analogs to target NPY receptors for tumor therapy." (PMID 22214201, 2011). "As in the case of NE and E, the angiogenesis-related growth-stimulatory actions of NPY are further modified by its direct effect on tumor cell growth and survival." (PMID 20508839, 2010). "We then examined whether NPY-induced fatty acid metabolism also exhibits an increased accumulation of lipids in the tumor cells." (PMID 40595538, 2025). "Importantly, ghrelin pre-treated neuron-conditioned media failed to rescue cancer cell proliferation under MK-0557 treatment suggesting inhibition of the NPY-specific growth-promoting effect on tumor cells." (PMID 40595538, 2025). "The neuropeptide Y/neuropeptide Y receptor system promotes BC cell proliferation, migration, invasion and metastasis and angiogenesis, whereas neuropeptide Y receptor antagonists inhibit all these effects and favor the death of tumor cells." (PMID 41301028, 2025). "Additionally, the recognition of tumor metabolic dependency on fatty acid metabolism unveils a promising pharmacological avenue to effectively suppress NPY-activated cancers in the brain." (PMID 40595538, 2025). "SP and NPY can also indirectly regulate tumor progression by affecting immune cells." (PMID 41415714, 2025). "It has also been shown that hypermethylated NPY circulating tumor DNA (meth-ctDNA) may be useful as a biomarker of CRC metastasis and progression and a potential indicator for last-line treatment with regorafenib in metastatic CRC patients." (PMID 39599612, 2024). "However, other studies indicated lower NPY expression in metastasis and in metastatic tumours with neuroendocrine differentiation." (PMID 36583743, 2023). "YR antagonists could exert an antitumor effect by inhibiting the tumor cell proliferation mediated by NPY." (PMID 37373115, 2023). "Accordingly, the main aim of this review is to update the currently available information on the involvement of NPY in cancer and suggest the use of NPY receptor antagonists as a promising antitumor strategy against tumor cells overexpressing NPY receptors (YRs)." (PMID 37373115, 2023).